JUN (Jun proto-oncogene, AP-1 transcription factor subunit)
Diseases named in the same sentence as JUN in open-access papers (continued):
Sharing a sentence is not in itself a finding about the gene and the disease.
cancer (continued). "In CRC, the expression of JUN was reported to be upregulated and play an important role in the cancer progression by making a complex with the TCF4 and β‐catenin (CTNNB1) transcription factors." (PMID 38872418, 2024). "In human bladder and cervical cancer, Sestrin2 expression enhanced the autophagy of cancer cells by modulating the Sestrin2-dependent MAPK8/JNK1/JUN mechanism." (PMID 39309448, 2024). "AP-1 transcription factors (TF) such as JUN, were initially considered as proto-oncogenes and deregulation of AP-1 family members was observed in several cancers." (PMID 38811984, 2024). "Following treatment with the encapsulated EO, a notable reduction in the expression of VIM, SLUG, SNAIL, and JUN, which are promoters of cancer cell invasion, was seen." (PMID 40259961, 2024). "Next, an online Kaplan-Meier plot was used to assess the predictive value of the PTGS2/ESR2/EGFR/JUN/MMP2 genes’ signature expression level on OS in numerous human cancers." (PMID 39707884, 2024). "JUN is known to promote cancer cell proliferation and Lin28A is a known oncogene that promotes cell cycle progression in cancer cells." (PMID 38000389, 2024). "JUN, a component of the AP-1 (Activator Protein-1) transcription factor, promotes invasion and metastasis in various cancers when overexpressed." (PMID 39401197, 2024). "Several malignant tumors express JUN, which is essential for regulating proliferation, apoptosis, and malignant transformation." (PMID 37375197, 2023). "As an important JNK effector, AP1 induces cancer differentiation but several aspects of c-JUN activity support a role in the prevention of tumorigenesis and inducing apoptosis." (PMID 37098530, 2023). "In detail, activated transcription factors, such as FOXO1, HIF1A, STAT3, and JUN, regulate the expression of TGFB1, TGFB3, IL1B, and TNF, promoting cancer hallmarks associated with these ligands." (PMID 37370765, 2023). "JUN has been reported to be overexpressed in diverse cancers including HCC and can play an oncogenic transcription factor." (PMID 37968735, 2023). "Heart, skin, kidneys, blood vessels, skeletal muscles, brain, liver, lungs, and adrenal glands are among the organs where AT1R is expressed, whereas c-JUN is mostly overexpressed in cancer tissue." (PMID 37368467, 2023). "We then investigated the correlation of JUN expression and the prognosis of patients with various cancer types." (PMID 37986345, 2023). "Taking OS as observation outcome, we found significant correlation between JUN expression and OS of 7 cancers: BLCA, BRCA, CESC, CHOL, LGG, LUSC, and THYM." (PMID 37986345, 2023). "JUNB is a transcription factor homologous to JUN, and JUN is specifically expressed in cancer tissues." (PMID 37452081, 2023). "Activated EGFR pathways and downstream MEK/ERK signaling were reported to promote AXL mRNA expression through the JUN transcription factor in a number of cancer cells." (PMID 37047640, 2023). "c-JUN, as a basic leucine zipper (bZIP) TF, takes part in many different cell functions, including proliferation, apoptosis, survival, cancer, and tissue morphogenesis." (PMID 37368467, 2023). "c-Jun, an oncogenic transcription factor, promotes cancer progression, invasion, and adhesion; high (JUN) mRNA expression correlates with poorer HNSCC survival." (PMID 38023989, 2023). "Across almost all cancer types, the motifs from the cluster JUN/FOS were highly enriched except for BRCA and PRAD." (PMID 35331302, 2022). "This kinase and its target transcription factor JUN have also been implicated in EMT, which is thought to be related to cancer migration." (PMID 36106411, 2022). "A high frequency of dysregulation in the chromatin remodelling pathway, especially PBRM1‐inactivating mutations and the PBRM1‐c‐JUN‐VIM axis, served as an important role of cancer invasion and was associated with poor patient outcomes in DPC." (PMID 36178086, 2022).
cancer (continued). "c‐JUN, known as a component of AP‐1, was first identified as a viral oncoprotein and is frequently activated in human cancers." (PMID 36178086, 2022). "In other studies, FOS and FOSB were found to increase cancer cell invasion, and JUN was involved in cancer cell invasion and metastasis." (PMID 35037412, 2022). "Here, the changes of three key molecules (IRS1, JUN and GSK3B) in the cancer-associated pathways were verified by real-time PCR and Western blotting." (PMID 36446361, 2022). "In response to the education by cancer cells, signal-regulated TFs like JUN are likely to be activated in CAFs." (PMID 36438487, 2022). "IHC results from the HPA database showed that JUN expression in cancer tissues was higher than that in normal liver and rectum tissues." (PMID 36091226, 2022). "It has been illustrated that synergistic activity of STAT3 and c-JUN were observed in human cancer specimens." (PMID 35955794, 2022). "On the other hand, antibody staining levels of JUN in ESCA cancer tissues were lower than those in adjacent tissues." (PMID 36091226, 2022). "JUN is involved in a wide range of cell processes including proliferation, apoptosis, survival, cancer, and tissue morphogenesis." (PMID 35899228, 2022). "Combinatory treatment with Sorafenib, mostly resulted with downregulation of hub proteins JUN, INSIG1, MDM2 and SOX9 associated with cancer cells." (PMID 35331184, 2022). "Many stimulatory signals, including oncoproteins and growth factors, activate c‐JUN‐dependent transcription and play important roles in carcinogenesis and cancer progression." (PMID 36178086, 2022). "Other studies have shown that the other two transcription factors (BMI1 and c­JUN) are dysregulated in a variety of cancers and inhibit PTEN transcription." (PMID 34006834, 2021). "It is noteworthy that KEGG pathway analysis of JUN, AR revealed that these gene are key members of the pathways in which small disruption will unfortunately leads to cancer." (PMID 34588861, 2021). "The hub gene TYMS is also involved in one carbon pool by folate pathway; FOS, JUN, and CDH1 genes are involved in pathways in cancer; and JUN and FOS genes are involved in the oestrogen signalling pathway." (PMID 32093341, 2020). "It is well established that Sp1 interacts with c-JUN in several cancers, and c-JUN acts synergistically with Sp1 to activate downstream oncogenes." (PMID 33230457, 2020). "miR-29 represses p85 (PIK3R1) and miR-30 targets JUN, both of which are important in cancer progression." (PMID 32211051, 2020). "The c-JUN/STAT3/PD-L1 axis is an important pathway in determining the immune evasion potential of cancer cells." (PMID 32855386, 2020). "As an important member of AP-1 transcription factor family, JUN is involved in growth, metastasis, and drug resistance of cancer." (PMID 32595734, 2020). "In Hp+-AG-IM network the expression of APOA4, GCG, CYP3A4, XPNPEP2 and FOXP3, JUN were statistically different in the comparison of normal and cancer in TCGA database." (PMID 32547867, 2020). "The key targets of GTF for cancer-related pain were Jun proto-oncogene (JUN), mitogen-activated protein kinase 1 (MAPK1), and RELA proto-oncogene (RELA)." (PMID 33224254, 2020). "It is worth noting that the expression of APOA4, GCG, CYP3A4, XPNPEP2, and FOXP3, JUN were different between cancer and normal samples in TCGA database." (PMID 32547867, 2020).
cancer (continued). "While little is known about the functional involvement of BRWD3 and PECR in human cancers, an enrichment of FOS as part of a heterodimer with JUN has previously been linked to anchorage-independent cell growth in our HPV-transformed cell lines as well as HeLa." (PMID 32188026, 2020). "Among these genes, EGR1, Fos Proto-Oncogene (FOS), FosB Proto-Oncogene (FOSB), Jun Proto-Oncogene (JUN), Dual Specificity Phosphatase 6 (DUSP6) and CTGF have been previously implicated in cancer metastasis." (PMID 30792382, 2019). "We also observed that other motifs were consistently enriched in either the normal or cancer tissue, including GATA in cancer, and JUN and CEBP family members in normal." (PMID 31520575, 2019). "By themselves, OCT4 and c-JUN showed less transformation activity, but the feedback between OCT4 and c-JUN increased the likelihood of cancer induction." (PMID 29259714, 2017). "We also found that c-JUN facilitates expression of pluripotent genes, such as Klf5, Zfp42, Dppa4 and Esrrb, which is consistent with previous observations that c-JUN plays a pivotal role in the maintenance of self-renewal in cancer stem cells." (PMID 27894081, 2017). "Further systems biology analyses revealed that this miRNA signature impacted oncogenic factors related to JUN and MYC and other important functions associated with cancer cell growth." (PMID 28107482, 2017). "DGIdb mining identified celecoxib, axitinib, and vinblastine, which interact with DDIT3, PDGFB, and JUN, respectively, with minimal interactions with other genes and proven anti-cancer effects." (PMID 27821810, 2016). "For example, ‘pathways in cancer (KEGG)’ is associated with eight different c-JUN TFBS gene sets, highlighting the role of c-JUN as a key factor of cancer progression." (PMID 24912499, 2014). "It is striking that the two gene families with the highest destabilization potential in the non-cancer cell line (JUN and FOSL) are actually found to be the two gene families with the highest destabilization role in the cancer cell line." (PMID 25182846, 2014). "Cancer cells are rapidly dividing and c-JUN is important for progression through the G1 phase of the cell cycle." (PMID 24466173, 2014). "Other members of the Jun family, such as JUNB and JUND, were found to have opposing functions to that of c-JUN, and in most cancers are observed to exhibit decreased expression." (PMID 21711548, 2011). "The results indicated both increased PPP1R15A and JUN expression levels in cancer tissues." (PMID 39948597, 2025). "This suggests that GPX3 and JUN may exert their anti-cancer effects in TC by regulating amino acid metabolism and influencing intracellular redox balance." (PMID 40092686, 2025). "Simultaneous PP2A activation and importin inhibition reduces nuclear levels of proteins that drive cancer progression and therapeutic resistance such as JUN, YAP, MYC, androgen receptor, hnRNPA1, and NF-κB under conditions where compounds that target PP2A or KPNB1 individually are inactive." (PMID 40588551, 2025). "JUN belonged to the most widely analyzed elements of the AP-1 complex and was engaged in numerous activities, including cell division, programmed cell death, survival, cancer development, and tissue formation." (PMID 40936936, 2025). "In contrast, FOS, EGR1, and JUN inhibit apoptosis, exacerbating cancer progression." (PMID 40740774, 2025). "MTLN loss has been associated with changes in mitochondrial calcium, ER contacts, mitochondrial superoxide, fatty acid oxidation, retrograde JUN signaling, and lipid metabolism, all with the potential to influence cancer progression or sensitivity to anti-cancer drugs." (PMID 40076565, 2025). "Consistent with previous results in cancer cell lines, JUN and FOS bound to many YAP/TEAD target sites (joint Y/T AP-1), but they also bound to AP-1 exclusive sites (AP-1 only), where no YAP/TEAD could be detected." (PMID 39210147, 2024).
cancer (continued). "JUN promotes the expression of cyclin D1, facilitating cancer cell proliferation." (PMID 40259961, 2024). "JUN also participates in cancer immunology and stem cell formation." (PMID 39390002, 2024). "Interestingly, AQP4_Astrocytes cluster derived from EPN highly expressed some anti-cancer genes, such as JUN, IRF1 and MSX1." (PMID 38383423, 2024). "Regulation of JUN expression is particularly important because its downregulation can lead to cell cycle defects and its upregulation can lead to accelerated cell proliferation, which occurs in some cancers." (PMID 38483896, 2024). "JUN has been known to be upstream of Axl and Mertk expression in cancer cells." (PMID 38561369, 2024). "JUN is a well-known oncogene involved in cancer progression." (PMID 37284849, 2023). "We also analyzed the expression of JUN in pan-cancer and the correlation of JUN expression and the prognoses for patients of different cancers and results indicated that JUN might be a promising therapeutic target for pan-cancer." (PMID 37986345, 2023). "Given that JUN is involved in resistance to gefitinib, genetic variation in drug resistance may explain the difference between 2D cells and cancer cells in vivo." (PMID 37434755, 2023). "Interestingly, in the majority of human cancers (bladder, breast, skin, cervical/endocervical, ovarian, lung and uterus), JUN expression was higher in normal tissues than in tumors." (PMID 36850002, 2023). "JUN works as a transcription factor which plays a crucial role in signal transduction pathways and is involved in cell division, motility, adhesion and survival in both normal and cancer cells." (PMID 37284849, 2023). "Similarly, we detected binding motifs for ELF3, KLF, and JUN in the cancer-enriched constituent enhancers of SE14." (PMID 35869079, 2022). "However, FOS and JUN were significantly downregulated in most of cancer compared to corresponding normal tissues." (PMID 35242279, 2022). "In this study, we described the mutational landscape and the unique molecular characteristics of DPC, especially PBRM1‐inactivating mutations and the PBRM1‐c‐JUN‐VIM axis, which serve as important methods of cancer invasion and were associated with poor patient outcomes in DPC." (PMID 36178086, 2022). "It was also observed that it increases expression of PD-L1 (Programmed death-ligand 1) through activation of c-Jun (the protein encoded by JUN gene, the component of activator protein-1 pathway) and further leads to exposure to the plasma membrane of cancer cells." (PMID 34068609, 2021). "The results indicated that these TFs—HIF1A, JUN, LEF1, and FOS—were negatively correlated with four glycolysis-associated lncRNAs across the five cancer types, suggesting that the low expression of these lncRNA signatures was accompanied by glycolytic signaling and oncogenic TF activation." (PMID 33627136, 2021). "Moreover, we unveiled that TPTEP1 confined AML cell proliferation through inactivating JNK/c-JUN signaling, a well-known oncogenic pathway verified in a variety of cancers, including AML." (PMID 33985519, 2021). "Among them, six transcription factors regulating the cancer stem cell-associated genes were verified by the reported literatures (marked with deep red), including NR4A1, FOS, KLF-4, GLI1, NFATC1 and JUN." (PMID 32242101, 2020). "Thus, our data strongly suggest that GATA2 and c‐JUN are TFs in addition to FOXA1 and HOXB13 that associate with ARBSs and regulate AR binding selectively in normal and cancer cells." (PMID 31520575, 2019).
cancer (continued). "The major reason for this inconsistency is largely due to the disparity of cancer types, which could interfere with the function of c-JUN, FBXW7, and NICD1 and result in the apparently contradictory properties of MAGE-A1 in cancers." (PMID 31640756, 2019). "For example, JUN and FOS are associated with cancer drug resistance and metastatic progression." (PMID 31623682, 2019). "AD-specific module AD_M3 is regulated by JUN, which target genes enriched in the pathway in cancer." (PMID 30598117, 2018). "Increased expression of JUN and FOS family members is associated with several cancers." (PMID 28427184, 2017). "When determining the impact of the miRNA signature on DLBCL biology, it was discovered that these miRNAs had the most prominent impact on genes, MYC and JUN, with global impact on cancer related functions starting at age several months before actual DLBCL formation." (PMID 28107482, 2017). "Our results showed that the levels of JNK and c-JUN protein in cancer tissues were both strong." (PMID 28666421, 2017). "Interestingly, STAT1[Gene ID: 6772], NFKB1[Gene ID: 4790] and JUN[Gene ID: 3725] genes, three crucial signaling molecules in cancer cells, have been further identified as common targets of the three compounds." (PMID 26359356, 2015). "The oncogene, c-JUN, was found to play a role in promoting the cell cycle through stimulation of Ras, specifically activating crucial cell-cycle regulators and thus inducing the G1-S transition and enhancing cancer development and progression." (PMID 21711548, 2011). "Importantly, no cancer-related pathways were upregulated; in fact, the JUN oncogene, which encodes the c-Jun transcription factor, was downregulated." (PMID 41511364, 2026). "In order to determine transcription factors in cancer-associated fibroblast activation, which play a role in cell proliferation and cancer progression, we evaluated the expression of several transcription factors, including SOX9, POU5F1, ZEB1, JUN, and FOS in the HRTPT cell line exposed to arsenite." (PMID 40699854, 2025). "Additionally, results of prognosis analysis indicated that JUN might be a promising therapeutic target for cancer." (PMID 37986345, 2023). "However, JUN overexpression leading to cell cycle progression and metastasis may generate or accelerate cancer." (PMID 36834821, 2023). "C-JUN, a proto-oncogene (its protein is JUN), is a cellular homologue of viral oncoprotein v-JUN, which is the major carcinogenic transcription factor found, and CCL2 can not only maintain the drug resistance of drug-resistant cancer cells but also cause drug resistance of sensitive cancer cells." (PMID 35321506, 2022). "That is a strong possibility given that several oncogenes are regulated by FBXW7, including MYC, Notch, JUN and cyclin E. Thus, targeting different pathways in addition to the mTOR pathway might be necessary to effectively kill cancer cells in tumors driven by FBXW7 alterations." (PMID 24586741, 2014). "Moreover, c-JUN is an apoptosis down-regulator, which is important for cancer cell survival." (PMID 24466173, 2014). "Collectively, these results suggest that the c-JUN pathway in lung fibroblasts can be activated by DKK1, contributing to the activation of inflammatory fibroblast traits and cancer cell-fibroblast interaction." (PMID 40025612, 2025). "In contrast, seven out of ten anti-AD core targets (PTGS2, MAPK1, MAPK3, JUN, ESR1, IL6, and PIK3CA) followed the pathways in cancer." (PMID 40179089, 2025). "The “High Signal” list affected 24 cancer drivers, encompassing key genes such as PIK3CA, MTOR, RAF1, and JUN." (PMID 39975128, 2025).